RNU6-198P (RNA, U6 small nuclear 198, pseudogene)
Gene: Small nuclear RNA gene on chromosome 2 (39,082,589 to 39,082,692, forward strand). Ensembl gene ENSG00000206985.
Homologues: Orthologues: chimpanzee U6 (99% identical), macaque U6 (90% identical), guinea pig U6 (82% identical), guinea pig U6 (80% identical), mouse Gm23138 (80% identical), dog U6 (73% identical), pig U6 (73% identical), rabbit U6 (73% identical), rat LOC120102584 (72% identical), mouse Gm23851 (71% identical). Paralogues in human: RNU6-16P (86% identical), RNU6-25P (86% identical), RNU6-1 (85% identical), RNU6-14P (85% identical), RNU6-2 (85% identical), RNU6-20P (85% identical), RNU6-35P (85% identical), RNU6-3P (85% identical), RNU6-4P (85% identical), RNU6-5P (85% identical), RNU6-6P (85% identical), RNU6-73P (85% identical), and 1289 more.